INS (insulin)
Diseases named in the same sentence as INS in open-access papers (continued):
Sharing a sentence is not in itself a finding about the gene and the disease.
Insulin resistance (continued). "Increase in serum insulin levels as well as random blood glucose levels, with increased HOMA –IR values indicated insulin resistance and dysglycemia in HFA and HFR groups as compared to CN group." (PMID 26098111, 2015). "The indicator for insulin sensitivity, ISI, also successively decreased in FH1 and FH2, while HOMA-IR, indicative of insulin resistance, showed an increase." (PMID 25664814, 2015). "Diets categorized by consistently high glycemic loads tend to predict insulin resistance and subsequent T2DM in both men and women, since chronically high insulin requirements to mediate glucose uptake can lead to reduced insulin sensitivity over time." (PMID 25710041, 2015). "The homeostasis model assessment of insulin resistance (HOMA-IR), a widely used estimate of insulin resistance in the fasting state, was calculated as fasting plasma insulin (FPI)-[mU/L] × fasting plasma glucose (FPG) [mmol/L]/22.5." (PMID 26089886, 2015). "Since this action has a clear association with insulin resistance, we questioned whether the induction of hepatic gluconeogenesis by GC-1 and KB2115 might contribute to the reduced glycemic control and the failure to improve insulin sensitivity in mice treated with these agonists." (PMID 25849936, 2015). "Fasting glucose and insulin levels were also increased in LFD-Creb3l4 KO mice, typical signs of insulin resistance." (PMID 26302066, 2015). "In order to understand the mechanism by which ApoA5 ASO-treated mice were protected from lipid-induced liver and muscle insulin resistance, we assessed DAG and ceramide content, nPKC translocation, and insulin-stimulated AKT2 phosphorylation in these tissues." (PMID 25548259, 2015). "Otherwise, ISI clamp-derived parameters mainly reflect skeletal muscle specific insulin sensitivity, whereas elevated HOMA-IR is commonly due to hepatic insulin resistance." (PMID 25025664, 2014). "In low protein rats, the liver insulin resistance was counteracted by the enhanced muscle AKT phosphorylation and expression that resulted in peripheral insulin sensitivity, reflected in the increased Kitt value." (PMID 25258479, 2014). "Our observation of the relatively normal fasting glucose and insulin levels, as well as normal range HOMA-IR values in our subjects suggests that neither pre- or manifest HD subjects have impaired glucose tolerance or insulin resistance." (PMID 25002850, 2014). "Furthermore, features of the metabolic syndrome, including degrees of obesity, showed an overall inverse trend across increasing quartiles of the PI/I ratio, paralleling that of HOMA-IR, indicating that extreme insulin resistance and insulin secretory deficit may depict different phenotypes." (PMID 25347846, 2014). "Impaired insulin secretion (IIS) and insulin resistance (IR) are the main pathophysiological components of type 2 diabetes, with the contributions of these factors thought to differ between Asians and whites." (PMID 25166121, 2014). "In support of this hypothesis, recent studies have clarified that defects in insulin signaling at the level of insulin receptor substrate (IRS) proteins are frequently associated with human insulin resistant states, resulting in the occurrence of cell-type specific insulin resistance." (PMID 24982885, 2014). "Fasting blood sugar (FBS), fructosamine, lipid profiles, fasting blood insulin (FBI), homeostasis model assessment of insulin resistance (HOMA-IR); beta cell function (b%), insulin sensitivity (S%) and malondialdehyde (MDA) were monitored." (PMID 25242840, 2014). "The researchers reported that the development of insulin resistance was characterized by increased levels of MAPK, NF-κB, and insulin receptor substrate 1 (IRS-1) serine phosphorylation while Akt expression and insulin contents were markedly reduced." (PMID 24566317, 2014). "In accordance, whole-body PTP1B knockout mice are hypersensitive to insulin and resistant to high fat diet (HFD)-induced insulin resistance." (PMID 25398386, 2014).
Insulin resistance (continued). "In contrast to the insulin resistance found in the liver of CD1d−/− mice, the WAT displayed an insulin sensitive phenotype with marked increase in PGC-1 and slight increase in PPAR-α." (PMID 24465369, 2014). "And FXR-null mice exhibited mildly impaired glucose tolerance and insulin sensitivity, while FXR activation reversed insulin resistance." (PMID 24872814, 2014). "In our study, HepG2 cells were used as an insulin resistance model to investigate the effect of FTZ on glucose metabolism and insulin signaling." (PMID 24555840, 2014). "Four weeks of TAC treatment increased blood glucose levels, hemoglobin A1c (HbA1c), the homeostatic model assessment of insulin resistance (HOMA-IR) index, and decreased insulin level." (PMID 24959755, 2014). "The active HMW form of adiponectin has been shown to correlate better with insulin sensitivity than TA, and has been shown to be low in HIV-infected patients with insulin resistance." (PMID 25580091, 2014). "Following 4 weeks of WY 14,643 treatment plasma levels of insulin, TG, FFA decreased compared to controls and also a decrease in insulin resistance was observed." (PMID 25486018, 2014). "Treatment with TNF-α induces insulin resistance in adipose tissue, whereas deletion of TNF-α or its receptors improves insulin sensitivity in obese animals." (PMID 24733068, 2014). "It was found that in high-fructose-fed rats, supplementary CrProp in both dosages was able to significantly decrease serum insulin levels and insulin resistance indexes HOMA-IR and HOMA-B, while it increased the QUICKI insulin sensitivity index." (PMID 24415067, 2014). "In insulin resistance that occurs in T2DM, the capacity of insulin to induce all these phosphorylation cascades is significantly decreased." (PMID 24574966, 2014). "Thus, a lack of mGluR5 might reduce susceptibility to diet-induced insulin resistance, since mGluR5−/− mice show decreased plasma levels of leptin and insulin, despite a 10-week high-fat diet." (PMID 24847259, 2014). "Indeed, an acute increase in peripheral insulin levels may increase insulin in cerebrospinal fluid, whereas chronic peripheral hyperinsulinemia (as in insulin resistance or T2D) may downregulate IRs at BBB, impair brain insulin uptake, and culminate in learning, memory, and cognition deficits." (PMID 25071725, 2014). "In a 5-year follow-up study of 1096 nondiabetics, the association between adiponectin and T2DM was attenuated after adjustment for homeostatic model assessment of insulin resistance (HOMA-IR) and was eliminated after adjustment for insulin sensitivity." (PMID 24860814, 2014). "Studies have shown that there is a defect in the glucose-stimulated insulin secretion, but other studies have found that insulin response is enhanced in women with PCOS, likely as compensation for the peripheral insulin resistance." (PMID 24705280, 2014). "Some simple methods of measuring insulin resistance includes fasting insulin, fasting plasma glucose (FPG)/fasting insulin (FINS), homeostasis model assessment method of insulin resistance (HOMA-IR), and 1/(FPG × FINS)." (PMID 25136362, 2014). "In all groups assessed in our study, fasting insulin had comparable correlations to those observed with the more complex indices of insulin resistance (HOMA-IR, QUICKI or FIRI) with clamp insulin sensitivity." (PMID 25106496, 2014). "Targeted mutations in PTRF/CAVIN-1 result in lack of caveolae in lung epithelium and, along with increases in insulin and free fatty acid levels, PTRF mutant mice show impaired glucose tolerance and insulin resistance." (PMID 24690998, 2014). "Systemic insulin resistance (IR) is a primary feature in non-alcoholic steatohepatitis (NASH), however, there remain limited data on tissue-specific insulin sensitivity in vivo." (PMID 24962805, 2014).
Insulin resistance (continued). "Several recent reviews explore the links between obesity, insulin resistance and the metabolic syndrome, and cancer highlighting the potential roles of hyperinsulinaemia, higher bioactivity of IGF-I, IGF-II and insulin through IR-A and IGF1R." (PMID 26237614, 2014). "The homeostatic model assessment of insulin resistance (HOMA-IR) and quantitative insulin-sensitivity check index (QUICKI) methods are commonly used for insulin resistance and insulin sensitivity, respectively." (PMID 24447396, 2014). "The insulin-Akt signaling and MAPK are the most important pathways involved in insulin resistance and oxidative stress." (PMID 25416469, 2014). "Serum insulin and C-peptide concentration during the OGTT and HOMA-IR (homeostatic model assessment–insulin resistance) were similar in hypoglycemic and euglycemic patients." (PMID 24736741, 2014). "Insulin resistance in T2DM, and the corresponding peripheral hyperinsulinemia, reduces insulin transport through the BBB, and the systemic insulin deficiency in T1DM increases tau phosphorylation." (PMID 25346723, 2014). "In other words, the application of insulin reagents via injections as the general practice in T2DM patients now is bound to aggravate insulin resistance in T2DM and increases the usage of insulin, leading to the chronic exposure to excess insulin." (PMID 24741073, 2014). "The animals in PCO group gained more weight, had higher plasma insulin and glucose levels and showed an elevation of HOMA-IR; an index of insulin resistance." (PMID 24762064, 2014). "It has also been reported that prolactin is involved in insulin resistance in WAT during lactation and suppresses insulin-induced leptin production in WAT." (PMID 24299740, 2014). "The homeostatic model assessment of insulin (HOMA-IR), β-cells function (HOMA-B%), fasting insulin resistance index (FIRI), and the quantitative insulin-sensitivity check index (QUICKI) were calculated." (PMID 25197274, 2014). "In the present study, we used Wistar rats to evaluate the effect of silymarin on insulin sensitivity and clarify the role of PTEN in silymarin-induced insulin resistance." (PMID 24404172, 2014). "However, while the lipogenic effects of insulin and the hyperinsulinemia that is characteristic of insulin resistance likely play a role in the accumulation of hepatic fat, it has long been suspected that hepatic lipids precipitate the development of insulin resistance." (PMID 25371775, 2014). "Insulin resistance was induced in the T2DM-NASH group as shown by hyperinsulinemia, increased HOMA-IR, and decreased insulin sensitivity index (ISI) as compared with the control group and the control-cele group." (PMID 24404139, 2014). "In animal models, the overexpression of human RBP4 or the injection of recombinant RBP4 induces insulin resistance in mice, whereas RBP4 knockout mice showed enhanced insulin sensitivity." (PMID 24559154, 2014). "Both GH resistance and insulin resistance are present in SGA subjects, which regulated by GH and insulin signals in metabolism and growth." (PMID 24963636, 2014). "It is possible that insulin resistance measured by glucose clamp or steady-state plasma glucose methods gives results different from HOMA-IR estimated from FPG and serum insulin." (PMID 25695028, 2014). "In animal models, mice become insulin resistant when liver synthesis of IGF-1 is deleted, and IGF-1 administration corrects this insulin resistance." (PMID 24586785, 2014). "Consistent with insulin resistance, patients with HUA had greater insulin secretion indices, that is, INSR30 and INSR120, than LUA in all groups." (PMID 24971368, 2014). "The insulin resistance index (HOMA-IR) and muscle insulin sensitivity index during the second hour of the OGTT were similar in patients with DM-NAFLD and those with T2DM only." (PMID 24397589, 2014). "Mice fed lingonberries, blackcurrants, and bilberries had lower fasting glucose and/or insulin, resulting in a lower HOMA-insulin resistance index." (PMID 24669315, 2014).
Insulin resistance (continued). "The commonly used homeostatic model assessment of insulin resistance (HOMA-IR) which utilizes fasting glucose and insulin has been validated against M across several populations (r = 0.5-0.8)." (PMID 24555815, 2014). "An important finding of this study is that the diet-induced diabetic condition captures many features of prevalent type II diabetes, evidenced by obesity, increased plasma insulin and MCP-1 protein, as well as the development of insulin resistance." (PMID 24886035, 2014). "In human studies, insulin resistance is related to plasma ADMA concentration and treatment with rosiglitazone and weight reduction enhance insulin sensitivity and significantly lower plasma ADMA level." (PMID 25467091, 2014). "The mechanisms by which insulin resistance develops are not yet fully understood but recent work has shown that forcing cells to accumulate fatty acids beyond their storage capacity may lead to insulin desensitisation through the generation of toxic lipid intermediates such as ceramide." (PMID 25058613, 2014). "It is, however, not clear whether insulin or insulin resistance are risk factors for AF." (PMID 25150967, 2014). "In fact, insulin resistance is found in 30–40% of women with PCOS, and it is characterized by resistance to the effects of insulin and in uptake in the metabolism of glucose with subsequent reduction of body's ability to eliminate glucose from the bloodstream." (PMID 24876842, 2014). "High doses of steroids, increase insulin resistance and certain immunosuppressive agents used to treat GVHD (such as calcineurin and mTOR inhibitors) inhibit insulin secretion and/or modulate insulin resistance." (PMID 25496809, 2014). "HFHSD raising was used to develop insulin resistance model; meanwhile, STZ enters the pancreatic β cell via a glucose transporter GLUT2 and induces a mild impairment of insulin secretion which is similar to the feature of the later stage of type 2 diabetes." (PMID 24738047, 2014). "In this study, participants were assessed using an OGTT followed by C-peptide deconvolution for ISR, calculation of the MI for insulin sensitivity, and comparison of relative BCF to insulin resistance using the DI." (PMID 24524730, 2014). "Treatment with hyperglycemia and chronic insulin or normoglycemia and the pharmacological OGA inhibitor, PUGNAc, result in the global elevation of O-GlcNAc modified nucleocytosolic proteins and insulin resistance in rodent adipocytes." (PMID 24948903, 2014). "Fat feeding resulted in persistent elevations in plasma insulin, TG and FFA levels and the HOMA insulin resistance index versus initial chow fed levels, seen after 1 week." (PMID 25486018, 2014). "It has also been shown that when measurements of beta-cell function were adjusted for severity of insulin resistance, subjects with IGT and combined IFG/IGT had a significantly greater reduction in insulin secretion than subjects with IFG." (PMID 25180037, 2014). "Homeostasis model assessment of insulin resistance index (HOMA-IR) was calculated from the fasting concentrations of glucose and insulin." (PMID 25551248, 2014). "The activity of the insulin-dependent Akt signaling pathway is highlighted because of its decrease in insulin-sensitive organs, like liver and muscle, which may underlie insulin resistance and hyperinsulinemia, and its increased levels in non-metabolic organs, such as kidney and aorta." (PMID 25239110, 2014). "The Homeostatic Model Assessment Insulin resistance (HOMA-IR), Matsuda index, and insulin sensitivity index (ISI 0, 120) were computed." (PMID 24981579, 2014). "Specifically, patterns of change in indices of insulin resistance (homeostasis model assessment of insulin resistance, HOMA-IR), insulin secretion (C-Peptide) and hepatic insulin extraction (C-Peptide/Insulin Ratio) were evaluated." (PMID 24733551, 2014).
Insulin resistance (continued). "Alterations of some of the insulin signaling pathways such as PI3K/Akt and GSK-3 are recorded in central inflammation and insulin resistance." (PMID 25346723, 2014). "Pioglitazone acts as an insulin sensitizer, decreasing circulating TG and FFA and ameliorating systemic insulin resistance in KKAy mice." (PMID 24799887, 2014). "Since insulin resistance and hyperinsulinaemia are central to the pathogenesis of PCOS, it is natural to expect insulin sensitisers to be of benefit in the management of the condition." (PMID 25139174, 2014). "Insulin, glucose, total serum cholesterol, HDL-C, LDL-C, total triglycerides, markers of plasma atherogenicity, and indices of insulin resistance were measured in all participants." (PMID 25243022, 2014). "Insulin resistance (HOMA-IR) and β-cell function (HOMA-β) were both calculated on the basis of the fasting levels of plasma glucose and insulin according to the homeostasis model assessment (HOMA) method." (PMID 25283478, 2014). "Meanwhile, the glucose tolerance test and insulin tolerance test revealed that mice fed with HFD for 12 weeks exhibited obvious abnormal glucose tolerance and insulin resistance." (PMID 24651118, 2014). "Under the condition of ER stress, activated c-Jun N-terminal kinase (JNK) inhibits insulin signaling through phosphorylation of IRS-1 at serine 307, leading to the development of insulin resistance." (PMID 24474199, 2014). "Blood biochemistry: total, HDL and LDL cholesterol, triglyceride, glucose and insulin and HOMA-index of insulin resistance at baseline and the end of each phase (n = 37)." (PMID 25379688, 2014). "There is a close correlation between severity of fatty liver and signs of insulin resistance (HOMA index, fasting blood sugar, fasting insulin level and clinical evidence of acanthosis nigricans)." (PMID 25031864, 2014). "Overexpression of MCH in mice leads to obesity and insulin resistance, and in contrast, pMCH−/− and MCH-neuron-ablated mice are lean with improved insulin sensitivity." (PMID 25084113, 2014). "Fasting plasma glucose levels were normal while plasma insulin levels (p < 0.01) and NEFA levels (p < 0.001) were significantly higher in the Old-Control and Old + GLP-1 groups suggesting insulin resistance." (PMID 25078106, 2014). "Because the HOMA index values suggested a systemic insulin resistance in L rats, we analysed the presence and activation of AKT, a key enzyme involved in the insulin-signalling pathway, to assess the onset of insulin resistance in the liver." (PMID 24663492, 2014). "Previous studies have shown that rats fed a HFD develop insulin resistance, and low-dose STZ is known to induce a mild impairment of insulin secretion." (PMID 25120610, 2014). "Homeostasis model assessment for insulin resistance (HOMA-IR) was calculated using fasting blood glucose and insulin levels." (PMID 25514561, 2014). "Increased JNK activity can develop insulin resistance, and JNK1−/− mice have improved insulin sensitivity and enhanced insulin receptor signaling during obesity." (PMID 27335818, 2013). "The homeostasis model assessment for insulin resistance (HOMA-IR), and quantitative insulin sensitivity check index (QUICKI) were selected as the insulin-related markers." (PMID 24719625, 2013). "TA effectively prevented HF diet-induced increases in the levels of blood glucose, insulin, leptin and HOMA-IR index (p < 0.001, p < 0.05, p < 0.05, p < 0.01, respectively) and attenuated insulin resistance." (PMID 23455665, 2013). "Animal studies in mice suggest that insulin signalling in osteoblasts increases the secretion of OC and thereby promotes glucose homeostasis via uncarboxylated OC and may thus prevent the development of insulin resistance, glucose intolerance and abnormal weight gain." (PMID 23658795, 2013).